ABCB1 (ATP binding cassette subfamily B member 1)
Diseases named in the same sentence as ABCB1 in open-access papers (continued):
Sharing a sentence is not in itself a finding about the gene and the disease.
Seizure (1 paper, 2021). A seizure is an intermittent abnormality of nervous system physiology characterized by a transient occurrence of signs and/or symptoms due to abnormal excessive or synchronous neuronal activity in the brain. "We found that patients with ABCB1 rs1045642, rs1128503 or rs2032582 TT genotypes were more prone to have seizures but those with rs1045642 TT developed PRES less frequently." (PMID 34066083, 2021).
skin reaction (1 paper, 2024). "Here, the patient carried the GG genotype of ABCB1 rs1128503 and presented with severe skin reactions." (PMID 39204145, 2024).
Spasticity (1 paper, 2025). A motor disorder characterized by a velocity-dependent increase in tonic stretch reflexes with increased muscle tone, exaggerated (hyperexcitable) tendon reflexes. "The main finding of this study is that the T allele in the ABCB1 rs1128503 (1236 C > T) and rs1045642 (3435 A > T) is predictive of response to NBX treatment in MS-related spasticity." (PMID 41024302, 2025).
toxicity (1 paper, 2018). The degree to which an agent can damage an organism. "The genotypes CT/TT at ABCB1 rs1045642 single nucleotide polymorphism (SNP), showed a protective effect for liver toxicity when compared with genotype CC (OR = 0.18, 95%CI 0.04–0.76; p = 0.020) in univariate analysis." (PMID 30419834, 2018).
urothelial carcinoma (1 paper, 2023). A malignant neoplasm derived from the transitional epithelium of the urinary tract (urinary bladder, ureter, urethra, or renal pelvis). "IL-8, a component of the SASP, was necessary for the increased expression of multi-drug resistance 1 (MDR1)/ABCB1 by chemotherapy in urothelial carcinoma endothelial cells." (PMID 36834846, 2023).
urothelial carcinoma of the urinary bladder (1 paper, 2021). "For patients diagnosed with urothelial carcinoma of the urinary bladder, upon DDP treatment, DDP‐induced CCAAT/enhancer‐binding protein delta expression activated ABCB1 and ABCC2, and the high expression of ABCB1 and ABCC2 resulted in a decline in the effect of DDP." (PMID 32815556, 2021).
vitamin A deficiency (1 paper, 2015). Deficiency of vitamin A due to malnutrition, malabsorption, or dietary lack. "In conclusion, vitamin A deficiency may alter Abcb1/P-GP expression and function in rat tissues, and the alterations may increase drug activity/toxicity through the increase of tissue accumulation." (PMID 26729079, 2015).
cancer (1,534 papers, 1990 to 2026). A tumor composed of atypical neoplastic, often pleomorphic cells that invade other tissues. "ABCB1 gene is associated with efflux transporter proteins that pump doxorubicin out of cancer cells." (PMID 40352931, 2025). "During hypoxia, cancer cells often increase the expression of ABC transporters such as P-glycoprotein (P-gp/ABCB1), multidrug resistance-associated proteins (MRPs), and breast cancer resistance protein (BCRP/ABCG2)." (PMID 39857427, 2025). "The ABCB1 efflux pump is also associated with multidrug resistance, a phenomenon that limits the efficacy of chemotherapy in cancer patients." (PMID 40697426, 2025). "In cancer, synonymous variants in genes such as ABCB1 (MDR1) can modulate the expression of efflux proteins, influencing the response to chemotherapy drugs." (PMID 41301675, 2025). "Some studies have also found a close relationship between the ABCB1 gene polymorphism and pain perception in cancer patients." (PMID 40873551, 2025). "As a prototypical member of the ABC transporter family, ABCB1 has been definitively implicated in chemoresistance across multiple cancers." (PMID 41462884, 2025). "For example, the overexpression of P-glycoprotein encoded by the ABCB1, a transmembrane transporter, has been shown to prevent the accumulation of chemotherapeutic agents such as doxorubicin and vincristine in cancer cells." (PMID 40968311, 2025). "We have previously shown that resistance of cancer cells to doxorubicin is associated with high level of the multidrug resistance protein 1 (MDR1/ABCB1) expression, which is due to its role in increasing the efflux of chemotherapeutic drugs." (PMID 40216647, 2025). "The results revealed a 25%–30% reduction in the expression of ABCB1 and ABCG2, which encode for P-glycoprotein and breast cancer resistance protein, respectively, in NFIB-overexpressed vs. control cells (P < .05)." (PMID 40554316, 2025). "Similar considerations regarding a potential use for combating multidrug-resistant cancer were made for tazemetostat, a triple inhibitor of ABCB1, ABCC1 (multidrug resistance-associated protein 1, MRP1) and ABCG2." (PMID 40284428, 2025). "It was reported that when ABCB1 is overexpressed, it is associated with cancer-stem cell-like properties and with the epithelial–mesenchymal transition." (PMID 39457585, 2024). "(b) An intron variant of ABCB1 (ATP Binding Cassette Subfamily B Member 1), a multi-drug pump involved in drug resistance to cancers." (PMID 39715885, 2024). "SRI, which was the only gene up-regulated at the mRNA and protein level in all three PR PDAC models alongside ABCB1, encodes the calcium-binding protein Sorcin that is associated with cancer progression and can activate expression of ABCB1." (PMID 38163893, 2024). "Although drug resistance in cancer involves multiple mechanisms, including mutations and altered gene expression, ABCB1 overexpression is one of the important mechanisms of drug resistance and cancer relapse." (PMID 39003409, 2024). "It is also worth pointing out that ABCB1 transports many cancer drugs very efficiently but still causes shifting levels of cardiotoxicity in patients, an observation that appears to be conflicting with ABCB1 serving a vital protective capability." (PMID 38576421, 2024). "For toxicity, a meta-analysis including cancer patients receiving docetaxel have found a significant association between ABCB1 3435TT genotype and a higher risk of developing hematological and neurotoxicity." (PMID 38962329, 2024). "Clinical studies have demonstrated that ABCB1 is overexpressed in various malignant tumor cells and is associated with chemotherapy efficacy and cancer progression." (PMID 39403600, 2024). "The MDR1 gene, also known as ABCB1, encodes a multidrug transporter P-glycoprotein (P-gp), which is closely associated with cancer resistance." (PMID 37789138, 2024). "Overexpression of ABCB1 has been linked to the development of chemotherapy resistance across these cancers." (PMID 37686513, 2023).
cancer (continued). "Several studies have shown that ABCB1 overexpression is associated with poor prognosis in various types of cancer, including breast, lung, colon, and ovarian cancer." (PMID 37367074, 2023). "The expression of ABCB1 causes chemotherapy failure owing to the efflux of drug molecules out of the cancer cell." (PMID 38304289, 2023). "SRI can drive the chemoresistance process and malignant progression by regulating the function of P-glycoprotein (P-gp) encoded by the ATP binding cassette subfamily B member 1 (ABCB1) gene in multidrug-resistant cancer cells." (PMID 35799174, 2022). "ABC transporters, particularly ABCG2 and ABCB1, have been linked to the SP phenotype for SP isolated from several other tissue types and cancer cell lines." (PMID 35118633, 2022). "The combination of rhMG53 and doxorubicin presents a potential new regimen to treat cancer patients that are both susceptible and resistant to chemotherapy due to ABCB1." (PMID 36147477, 2022). "In conclusion, our study strongly demonstrates that the overexpression of ABCB1 is associated with the resistance of ARS-1620 in cancer cells, which provides a valuable basis for future using of ARS-1620 in clinical studies." (PMID 35281897, 2022). "Numerous associations’ studies and meta-analyses have established the impact of the ABCB1 rs1045642 genetic variant in cancer treatment outcomes concerning chemotoxicity, overall survival, and therapeutic responses." (PMID 36432633, 2022). "The protein product of this gene takes part in vitamin B12 metabolism and has been jointly associated with ABCB1 in a study of cancer cell drug resistance." (PMID 36445690, 2022). "ABCB1—also known as multidrug resistance protein 1 (MDR1) and P-glycoprotein (P-gp)—has been linked to taxane resistance in various cancer entities including mCRPC." (PMID 36614114, 2022). "RNA sequencing of cancer cells in this study revealed ABCB1 and ABCG2 to associate with resistance to topoisomerase inhibitors." (PMID 35719112, 2022). "We still do not have a clear answer concerning the level of contribution of ABCB1 genetic variants to cancer risk or therapy response." (PMID 35627114, 2022). "A high frequency of responsive AS, mainly SE events, were induced by CDK6, CDK4, and PI3K 110α/β level changes, and these AS events finally led to the alteration of the ABCB1 expression and ABCB1-mediated MDR in cdk6 or cdk4 deficient KB-C2 cancer cells." (PMID 35459184, 2022). "Additional putative targets of miR-129-5p that are associated with drug resistance in cancers are ABC transporters (ABCB1, ABCC5, ABCG1) and RUNX1." (PMID 34063443, 2021). "The ABCB1 drug transporter is considered to be a common cause of chemoresistance in many cancers, including AML." (PMID 34298843, 2021). "Research from the past few years have concluded that P-glycoprotein (P-gp/ABCB1) is one of the major causes of MDR in cancers; although, studies about different transporters are in progress." (PMID 35006446, 2021). "A high level of ABCB1 expression has been associated with reduced chemosensitivity in a plethora of cancers such as breast, ovarian, pancreatic, and colorectal cancer." (PMID 35070633, 2021). "As overexpression of ABCB1 is one of the key factors leading to cancer MDR, we next sought to solidify the association of SLC25A40-ABCB1 fusions with resistance to standard of care HGSOC chemotherapeutic agents." (PMID 34830797, 2021). "One of the most probable explanations for reduced drug efficacy in ABCB1- and ABCG2-overexpressing multidrug-resistant cancer cells is the reduced intracellular drug accumulation caused by ABCB1- and ABCG2-mediated drug efflux." (PMID 33807514, 2021). "Multidrug resistance (MDR) associated with the over-expression of the transporters of vast substrate specificity such as ABCB1 (P-glycoprotein) belongs to the main causes of cancer chemotherapy failure." (PMID 34361789, 2021).
cancer (continued). "ABCB1 is responsible for the cellular transport, being an efflux pump, and is commonly associated with various types of cancers, due to its role in the multidrug resistance (MDR)." (PMID 34300228, 2021). "On the other hand, ABCB1 was consistently associated with intrinsic or acquired multidrug resistance and treatment failure in several cancer types." (PMID 33995103, 2021). "In various MDR cancers, lower levels of miRNAs targeting mRNAs of Wnt/β-catenin signaling components were associated with increased ABCB1 expression." (PMID 35582031, 2021). "ABCB1 expression can also be modified by single nucleotide polymorphisms (SNPs), which play an important role in cancer therapy, gene rearrangements, mutations, epigenetic regulation, and post-translational mechanisms." (PMID 35582031, 2021). "The ABCB1 gene belongs to ATP binding cassette (ABC) transporter genes that has been previously implicated in cancer progression and drug response." (PMID 32277145, 2020). "We further examined the frequency of this mutation in R7, RVC and RDC cells, as well as, in 24 ABCB1-expressing human cancer samples." (PMID 34541464, 2020). "ABCB1 is one of the major adenosine triphosphate (ATP)-binding cassette (ABC) transporters that can actively efflux a range of anticancer drugs out of cancer cells, causing MDR." (PMID 32466597, 2020). "Numerous studies indicate that the members of the ABC transporter family associated with multidrug resistance (MDR) in cancer cells include p-glycoprotein (P-gp/ABCB1), MRP1/ABCC1, MRP2/ABCC2, MRP4/ABCC4, and BCRP/ABCG2." (PMID 32164712, 2020). "The treatment-emergent selection of promoter-translocated ABCB1 variants provides compelling evidence for a central role of drug efflux in chemotherapy resistance, at least in cancers of ovary and breast." (PMID 33167906, 2020). "The transporter ABCB1 has been linked to migration, invasiveness, and metastatic ability of several cancers." (PMID 32587767, 2020). "Previous studies have reported that tyrosine kinase inhibitors (TKIs) such as imatinib and sunitinib are transported substrates of ABCB1 and ABCG2 and the overexpression of ABCB1 or ABCG2 in cancer cells results in reduced susceptibility to TKIs." (PMID 31941029, 2020). "Herein, we confirm the direct effect of sunitinib in cancer cells as well as demonstrate the association between YB-1 and ABCB-1 in sunitinib-resistance development in metastatic clear-cell RCC (mccRCC)." (PMID 32041631, 2020). "Efflux of chemotherapeutic agents by ABCB1 is an important cause of treatment failure in human cancer." (PMID 31770110, 2020). "ABCB1 overexpression in MDR cancer cells is frequently associated with altered expression or activity of transcription factors, but also with gene rearrangements and mutations in the ABCB1 promoter." (PMID 33066132, 2020). "Patients with this type of cancer often develop brain metastases, which are difficult to treat with erlotinib, most likely due to its low brain distribution caused by ABCB1/ABCG2-efflux transport at the BBB." (PMID 33153231, 2020). "Among others, drug resistance in cancer cells is often caused by increased expression of the ABC subfamily B member 1 (ABCB1), which is also referred to as multi-drug resistance protein (MDR) 1 and permeability glycoprotein (P-gp)." (PMID 32391276, 2020). "The development of multidrug resistance (MDR) in cancer patients, which is often associated with the overexpression of ABCB1 (MDR1, P-glycoprotein) in cancer cells, remains a significant problem in cancer chemotherapy." (PMID 32466597, 2020). "Novel unpredicted interactions were found between leptin receptor, STAT3, and ABCB1, which has been linked to the development of drug resistance in cancer cells." (PMID 32471192, 2020). "We also examined the mutational spectrum of ABCB1 in diverse types of cancer samples including AMLs in the Cancer Genome Atlas (TCGA) at the National Cancer Institute." (PMID 34541464, 2020).
cancer (continued). "Overexpression of ABCB1 in cancer cells is one of the known factors associated with poor therapeutic response in patients receiving cytotoxic anticancer agents." (PMID 32466597, 2020). "This database offers a great opportunity to define the mutational spectrum of ABCB1 in human AMLs as well as in other types of cancer." (PMID 34541464, 2020). "ABCB1 is one of the major drug efflux transporters that is known to cause multidrug resistance (MDR) in cancer patients receiving chemotherapy for the treatment of solid tumors and hematological malignancies." (PMID 30641875, 2019). "Another classic example is P-glycoprotein, encoded by ABCB1, for which mutations causing overexpression can result in multidrug resistance in cancer cells." (PMID 31105571, 2019). "The most studied members of the ABC-family of drug efflux pumps in cancer are ABCB1/MDR1/P-gp (P-glycoprotein), ABCC1 and ABCC2 (multi-drug resistance associated proteins 1 and 2; MRP1 and MRP2 respectively), and ABCG2 (breast cancer resistance protein; BCRP)." (PMID 32382711, 2019). "In some cases, the functional role of gene amplification in cancer has already been uncovered, like the ABCB1 gene encoding the P-glycoprotein, which is an ATP-dependent efflux pump." (PMID 31134286, 2019). "Cancer cells acquire ABCB1 overexpression after prolonged chemotherapy, which is one of the major causes of cancer relapse since ABCB1-mediated drug efflux can reduce drug intake." (PMID 31249297, 2019). "Pgp expression, which is encoded by the ABCB1 gene, is closely related to cancer chemotherapy resistance." (PMID 31137684, 2019). "To date, there have been several clinical studies evaluating the correlation between ABCB1 gene polymorphisms with clinical data, including drug metabolism and risk of cancer." (PMID 30455395, 2019). "Wnt/β-catenin is one of the signaling pathways regulating the transcription of ABCB1 and causes multidrug resistance in cancers." (PMID 31861937, 2019). "Apart from the fact that ABCB1 remains one of the major cause of chemotherapy resistance in cancer, this transport protein play an important role as export pump of endogenous compounds and exogenous toxic agents in a variety of cells and tissues." (PMID 29317984, 2017). "It was discovered that ATP-binding cassette subfamily B member 1 (ABCB1) overexpression, which was associated with cancer stem cell (CSC) properties and EMT, was involved in the acquired resistance to MET inhibitors." (PMID 27757846, 2017). "In contrast, transporters implicated in drug resistance of cancer cells were upregulated in hiPS-Hep cells, including ABCB1 (MDR1) and ABCG2 (BCRP)." (PMID 28137721, 2017). "A high expression of ABCB1 has been associated with a poor prognosis in various cancers, including hepatic carcinoma, colon carcinoma, kidney cancer, osteosarcoma, soft tissue sarcoma and hematological malignancies, including leukemia and lymphoma." (PMID 28677036, 2017). "PPD has a high degree of anti-cancer activity, causing inhibition of ABCB1 in tumor cells and exhibiting extremely low toxicity." (PMID 26824187, 2016). "In cancer cells, failure of chemotherapy is often caused by the ATP-binding cassette subfamily B member 1 (ABCB1), and few drugs have been successfully developed to overcome ABCB1-mediated multi-drug resistance (MDR)." (PMID 26824187, 2016). "We determined that our established PTX-resistant cancer cells display ABCB1/ABCC1-associated cross-resistance to chemically different drugs such as 5-fluorouracil, docetaxel, and cisplatin." (PMID 27284014, 2016). "ABC transporters including ABCB1 have been reported to be implicated in promoting cancer stem cell (CSC)-like properties." (PMID 25875914, 2015). "For BRCA1- group we observed a significant increase in cancer risk for the heterozygotes carrying silent polymorphism p.Ile1145 = in the ABCB1 gene (OR 1.64; 95% CI 1.03-2.60; p = 0.036)." (PMID 25591549, 2015).